EGFR (epidermal growth factor receptor)
Diseases named in the same sentence as EGFR in open-access papers (continued):
Sharing a sentence is not in itself a finding about the gene and the disease.
tumor (continued). "One patient whose tumor harbored an EGFR exon 19 insertion had a partial response and was on osimertinib for 16.8 months." (PMID 36879929, 2023). "Folate receptors and epidermal growth factor receptors (EGFR) are overexpressed in tumor cells compared to normal cells." (PMID 37444386, 2023). "Targeted therapeutic treatments with CDK4/6 and EGFR inhibitors have been reported to potently reactivate repetitive elements within tumor cells, leading to cell death." (PMID 37638338, 2023). "The gene and protein expressions of VEGFA, E-cadherin, TGFβ1, EGFR, and bFGF in tumor cells were assayed at the 3 different doses of the anti-PD-L1 antibody." (PMID 38152616, 2023). "Regarding radiosensitivity, the activation of the EGFR signaling pathway in tumor cells induces radioresistance." (PMID 37629008, 2023). "Despite the promising results of drugs targeting EGFR in tumours, their complex drug resistance cannot be ignored." (PMID 37542324, 2023). "LUAD PDO carrying EGFR and BRAF mutations successfully captures the clinical response of the tumor to Dabrafenib/Trametinib combination therapy." (PMID 36696006, 2023). "HSV gD has been additionally harnessed to target various other tumor-specific proteins, including EGFR (oHSV R611), CAE (oHSV-KNC), PSMA (oHSV-R593), and EGFRvIII (oHSV-KNE)." (PMID 38005938, 2023). "In an EGFR-positive orthotopic lung tumor model, systemic injection of OA/DCN-shMet/PPE has been found to result in a remarkable 14.9-fold suppression of tumor growth with respect to naked Ad, thus causing total tumor regression in 66% of treated animals." (PMID 38009779, 2023). "Our work highlighted the crucial role of the tumor cell-rCAF crosstalk in contributing to cancer chemoresistance through the TGFα-EGFR paracrine signaling pathway." (PMID 37821657, 2023). "It leads to uncontrolled cell proliferation and tumor formation, which has been shown for EGFR to occur in breast, colon, ovarian, and pancreatic cancer cells." (PMID 37501139, 2023). "In this regard, most approaches were based on the peptide GE11 as a tumor targeting vector, which has been described to exhibit a very good EGFR targeting ability." (PMID 37259420, 2023). "Seven tumours from four patients showed 89Zr-anti-EGFR uptake, and 18 tumours from five patients showed 89Zr-anti-HER3 uptake." (PMID 36820891, 2023). "TCM and its active ingredients with great anti-tumor activity augment the efficacy of EGFR-TKIs in NSCLC." (PMID 36008690, 2023). "Some RTKs, such as epidermal growth factor (EGFR), can contribute to tumour spreading by establishing a molecular complex with integrin, inducing genetic aberrations and inducing treatment resistance." (PMID 38414954, 2023). "Specific lipid-based NPs have been created to deliver DTX and RSV in the mitochondria of EGFR-expressing tumor cells to overcome multi-drug resistance." (PMID 37754880, 2023). "The co-inhibition of the PELI1 and EGFR effectively suppressed the migration, invasion and tumor sphere formation ability and metastasis of MDA-MB-231 cells." (PMID 36841821, 2023). "If the tumor proves to be T790M-positive, selective EGFR TKIs designed especially for mutant EGFR, for example, osimertinib, can be an option." (PMID 38201251, 2023). "These enzymes are associated with the human epidermal growth factor receptor (EGFR), by inhibiting tyrosine kinase, gefitinib and erlotinib prevent EGFRs from stimulating uncontrolled cell growth that contributes to tumor growth." (PMID 37752494, 2023). "Amplifications of EGFR and ERBB2 were found only in immune deficient MPNSTs (n = 3 tumours with ≥15 additional copies of EGFR and n = 1 tumour with 9 additional copies of ERBB2)." (PMID 37837931, 2023).
tumor (continued). "OPB-51602, a specific ETC complex I inhibitor displayed significant tumor regression in patients with secondary resistance to epidermal growth factor receptor inhibitors in a phase 1 clinical trial." (PMID 38077060, 2023). "Biopsies have demonstrated that CAR T cells targeting EGFR can infiltrate tumor tissue and promote EGFR-targeted cytotoxicity." (PMID 37345192, 2023). "The outcome of stable disease is consistent with preclinical studies showing that DS‐1205c restored the antitumor activity of erlotinib in an erlotinib acquired‐resistance EGFR‐mutant NSCLC tumor xenograft mouse model." (PMID 36621830, 2023). "The scFv antibody-conjugated AuNPs can identify the epidermal growth factor receptor (EGFR) of tumor cells." (PMID 37176223, 2023). "Lnc-EGFR is highly expressed in tumor-infiltrating lymphocytes, and its expression is positively related to Treg content, Foxp3 expression, and tumor size, but negatively related to IFN-γ expression." (PMID 38933287, 2023). "Initial IHC analysis of HER2-type human BC specimens in the Oulu cohort (n = 21) showed that ColXVIII was highly expressed in HER2+ and EGFR+ tumor areas that had a high number of Ki67+ proliferating cells." (PMID 37498672, 2023). "β-catenin directly interacts with c-erbB-2 protein and EGFR, playing a crucial role in the tumor signaling pathway." (PMID 37537585, 2023). "It has been reported that EGFR mutations and ALK rearrangements play a significant role in the invasion of circulating tumor cells through the blood–brain barrier (BBB) and tumor angiogenesis, resulting in BM in NSCLC patients." (PMID 37573417, 2023). "The involvement of the recently described EGFR/HSP90/PPAR β/δ pathway in tumor cell metabolism, proliferation, and chemoresistance suggests a wider role of PPAR β/δ, one that includes cancer development and the resistance to therapy." (PMID 37048084, 2023). "In contrast, gefitinib exerted minor effects on the protein expression in tumor cells harboring different EGFR genotypes." (PMID 37371816, 2023). "Nimotuzumab requires bivalent binding in conditions of high EGFR cell surface density for stable receptor docking and has a low affinity for normal tissue receptors, allowing it to selectively bind to EGFR-overexpressing tumor cells." (PMID 37152586, 2023). "Pyrotinib inhibits tumor cell growth by blocking the formation of homodimers and heterodimers of EGFR and HER2 in tumor cells, inhibiting their phosphorylation, and blocking the activation of downstream signaling pathways." (PMID 36890831, 2023). "Accordingly, the organoids derived from this patient’s tumour showed resistance to cetuximab, which suggests a potential for tumour organoids to predict patient response to anti-EGFR therapy better than molecular biomarkers alone." (PMID 36765763, 2023). "We aquired EGFR mutations status including variant allele frequency (VAF) and mutation subtype in each tumor tissue by genetic test." (PMID 37035883, 2023). "Our results demonstrated that midazolam exhibited anti-tumor effects on NSCLC by regulating EGFR/MEK/ERK pathway." (PMID 37305523, 2023). "The EGFR participates in the key processes of tumor cell invasion and tumor-related angiogenesis and its upregulation correlates with poor prognosis in several human tumor types." (PMID 37762316, 2023). "The authors pointed to a dual effect involving the successful sensitization of EGFR-wt to erlotinib, potent tumor inhibition, and bevacizumab-induced normalization of the tumor-embedded vessels in a mouse model." (PMID 36865093, 2023). "Although FTY720 was found to inhibit basal-like tumor cell growth when combined with EGFR inhibitors, it is unclear which subsets of TNBC patients would benefit from this treatment." (PMID 37048053, 2023).
tumor (continued). "Of the 21 EGFR ex20ins patients with tumour PD-L1 expression of 50% or higher, 7 patients had received immunotherapy as monotherapy, 5 had received first-line pembrolizumab, and 2 had received pembrolizumab in the second-line or beyond setting." (PMID 37622996, 2023). "We showed that BBR and erlotinib synergistically suppressed tumor growth by acting on the common EGFR/AKT signaling pathways in EGFR positive cells." (PMID 37170144, 2023). "For example, PCDH10 was directly engaged in the negative regulation of the epidermal growth factor receptor signaling pathway, resulting in tumor suppression." (PMID 37147733, 2023). "Afatinib’s distinctive anticancer therapeutic benefit—its irreversible binding to ErbB family receptors—offers higher potential to suppress the proliferation of a wide class of tumor cells and greater efficacy than the first-generation EGFR-TKIs." (PMID 37366888, 2023). "The results revealed that the EGFR mutation and the TERT mutation had a significant association with tumour recurrence." (PMID 37892022, 2023). "Recently, there have been increasing studies regarding the role of the tumor microenvironment in the treatment efficacy of EGFR-TKIs, including the programmed death 1 (PD-1) and programmed death-ligand 1 (PD-L1) pathways." (PMID 36894581, 2023). "They found that one tumor clone had EGFR, CDK6, and MET amplification, while another subclone had PIK3CA amplification due to receiving a copy of chromosome 3." (PMID 38002496, 2023). "Some of these mutations, such as in-frame base pair insertions in exon 20 (ex20-ins), result in tumor resistance to conventional EGFR tyrosine kinase inhibitors." (PMID 36900399, 2023). "characterized that blocking EGFR by vandetanib in liver cancer models yielded a significantly reduced tumor vessel density and tumor growth, while enhancing tumor cell apoptosis and survival prolongation with reduced number of intrahepatic metastases." (PMID 37261338, 2023). "In this study, we identified that cytotoxic and exhausted CD8+ TILs with a tumor-reactive phenotype express the co-stimulatory receptor CD27 across various EGFR+ cancer subtypes." (PMID 37545491, 2023). "Our results showed that both the EGFR inhibitors reduced the cell viability in a dose-dependent manner; however, the afatinib was a more potent inhibitor of tumor-cell viability than the erlotinib." (PMID 36769112, 2023). "The aim of this study was the prevalence of acquired genomic alterations detected in the auxiliary tool of ctDNA testing and investigated the role of RAS ctDNA status for detecting tumour response and predicting benefit to anti-EGFR therapy." (PMID 37488448, 2023). "This research indicated a notable increase in cytokine secretion following the incubation of EGFR-CAR-T-cells with target tumor cells." (PMID 37457699, 2023). "Since high expression and functional activation of EGFR correlates with the pathogenesis of some cancers, EGFR can serve as an attractive target for both the diagnosis and therapy of neoplasia." (PMID 37111769, 2023). "-Activate EGFR/MAPK signaling.-High expression is positively correlated with tumor = invasive potential and poor prognosis." (PMID 38003931, 2023). "Conversely, a few studies show that miR-107 accelerates the tumor progression via amplification of EGFR and Wnt signaling." (PMID 37744274, 2023). "It was suggested that EMT fosters a detachment and invasion of tumor cells to form buds of therapy-resistant cells, hence our interest in the role of EGFR-EMT in local invasion." (PMID 37620936, 2023).
tumor (continued). "For the relatively moderate EGFR-expressing tumor line, Detroit 562, PAI outperformed SAI in all categories except sensitivity and was only narrowly better in negative predictive value (NPV)." (PMID 34651290, 2023). "We used immunohistochemistry in FFPE tumor samples to investigate the protein levels of EGFR and pY1068-EGFR." (PMID 36769112, 2023). "EGFR inhibitors, as the only approved targeted drugs, have limited efficacy and face the problem of tumor drug resistance." (PMID 37397383, 2023). "In summary, our results show that the ablation of N-WASP expression accelerates KRas-mutant-induced tumor formation through the activation of the EGFR-KRas signaling pathway." (PMID 37760426, 2023). "EGFR-XPAT protein confirmed the utility of XPAT technology for tumor targets more widely expressed in healthy tissues." (PMID 36997747, 2023). "In view of this, targeting EGFR is considered an efficient goal for the development of new anti-cancer agents that inhibit tumour angiogenesis and consequently tumour growth." (PMID 37165800, 2023). "We also identified genes encoding membrane receptors (IL7R, OSMR, EGFR) and transcriptional regulators (BNC2, BNC1, HMGA2, KLF7, NR3C1) as enriched in Basal tumours." (PMID 36944729, 2023). "In tumor cells, increased secretion of exosomes and selective enrichment of specific cargo proteins including integrins, EGFR, Jagged-1, or PD-L133,73,75–77 to the exosomes have been observed in response to oncogenic signaling." (PMID 37898620, 2023). "MMP14 activity mediated proteolytic processing to activate HB-EGF, stimulating the EGFR signaling pathway to increase proliferation and promote tumor growth." (PMID 36656313, 2023). "The crosstalk between oxidative stress and the EGFR-related pathway is an important regulatory mechanism in carcinogenesis, tumor progression, and therapy resistance." (PMID 36672272, 2023). "Aggravated MET signaling stimulates downstream signal transduction evading tumor cell death by EGFR-TKIs." (PMID 37970206, 2023). "Thus, patients with EGFRm+ NSCLC with true high-level MET amplification at baseline may harbor clones of MET-driven tumor cells that may very rapidly take over when EGFR signaling is inhibited and may cause intrinsic resistance to EGFR-TKIs, resulting in very rapid cancer progression." (PMID 37685884, 2023). "Treatment with α-EGFR/α-CD16/α-4-1BB NPs had the most robust treatment responses with tumor growth delays averaging 24 days after initial treatment and prolonged survival averaging 18 days compared to the nontreatment group (P=0.0018)." (PMID 37457707, 2023). "This approach aimed to explore the potential synergistic effects of both EGFR targeting and immune system activation in combating tumor growth within the challenging triple-negative breast cancer model." (PMID 37775519, 2023). "57% of tumours display some form of alteration in EGFR and among the classical subtype, EGFR is overexpressed in more than 95%." (PMID 37803333, 2023). "Regarding the predictive role, a metanalysis of 13 randomized controlled trials, investigated the correlation between efficacy of first-line therapy (bevacizumab vs anti-EGFR-based treatment) in mCRC patients and primary tumor location." (PMID 36895480, 2023). "We have previously reported the synthesis and characterization of a dual function antibody conjugate (DFAC) for multi-modal imaging (photoacoustic and fluorescence imaging) and PIT of EGFR over-expressing tumor cells." (PMID 36778405, 2023). "By contrast, various inhibitors targeting EGFR can effectively keep the proliferation of tumor cells and induce apoptosis." (PMID 37434393, 2023). "In 2014, Hongsheng Miao observed that EGFR vIII-CAR-T cells proliferated in the tumor region and inhibited the growth of tumor cells, improving the survival rate of experimental mice." (PMID 37190280, 2023).
tumor (continued). "AZD9592 monotherapy in vivo in patient-derived xenograft models showed a 30% reduction of tumor in 41% of EGFR mutant NSCLC tumors at 2 mg/kg and a 73% response rate in those treated at 8 mg/kg." (PMID 38107063, 2023). "Looking at these results, it can be said that the decreased VEGFA, E-cadherin, TGFβ1 and EGFR expression in PD-L1 low tumor cells after treatment is specific to anti-PD-L1 MoAb treatment." (PMID 38152616, 2023). "As presented in our cases, we recommend performing tumor rebiopsies in patients progressing on EGFR-TKIs, if feasible, to enable the next treatment based on a biomarker-matched approach." (PMID 37685884, 2023). "EGFR is one of the major driver genes in NSCLC, and approximately 10% of American NSCLC patients and 35% of Eastern Asian NSCLC patients carry tumor-associated mutations in the EGFR gene." (PMID 37089959, 2023). "Together, our results demonstrate that the reduction of sialic acid on tumor cells, obtained by sialyltransferase inhibition, enhances the in vivo anti-tumor activity of EGFR-targeting antibodies." (PMID 37346044, 2023). "The technology of pH-sensitive and anti-epidermal growth factor receptor (anti-EGFR) immunoliposomes aims to increase the selective delivery of the drug in the acidic tumor environment to cells with EFGR overexpression." (PMID 36986777, 2023). "We found that EGFR inhibition was synthetically lethal with KRASG12D blockade, as co-targeting KRASG12D and EGFR resulted in more potent cell apoptosis in vitro and tumor shrinkage in vivo." (PMID 37020035, 2023). "In this work, we have generated potent NKCE formats that bridge NKp46 on NK cells with EGFR on tumor cells." (PMID 36775946, 2023). "This ICAM-1 upregulation permitted EGFR CAR-T cells to move from tumor edge to center, and blockade of ICAM-1/LFA-1 disrupted the CAR-T cell tumor infiltration." (PMID 36895477, 2023). "Our study supports these studies and clinical observations; crosstalk between tumor and fibroblasts cell played role in EGFR TKI resistance." (PMID 36647832, 2023). "miRNA-7 is a tumor suppressor whose reduced expression level in GBM correlates with a high level of EGFR, which leads to uncontrolled cell proliferation." (PMID 37371047, 2023). "Of those, 19 (25%) patients had a R-sided tumor (9 patients received anti-EGFR treatment and 10 patients R/T) and 57 (75%) patients had a L-sided tumor (30 patients received anti-EGFR treatment and 27 patients R/T)." (PMID 36895480, 2023). "In all four xenograft models, triplet combinations resulted in statistically significantly improved tumor growth inhibition as compared to BRAF + EGFR or BRAF + SRC inhibitor doublets." (PMID 36759733, 2023). "CAFs cooperate with tumor cells to promote the formation and maintenance of the tumor microenvironment by activating multiple signaling cascades, including the EGFR, JAK/STAT, TGF-β, and Wnt signaling pathways." (PMID 36982677, 2023). "Stomach carcinogenesis is on account of overexpression of epidermal growth factor receptor (EGFR) in 27–44% of the initial tumor patient." (PMID 36985578, 2023). "EGFR overexpression has been recognized as a key factor in tumor growth, angiogenesis, metastasis, and therapy resistance." (PMID 37344903, 2023). "It has also demonstrated its ability to potentiate the anti-tumor activity of cetuximab in EGFR-positive HNSCC in a mouse model." (PMID 36992219, 2023). "Our previous work has confirmed that YAP1 regulated the stemness and promoted the growth of tumor cells, and it was closely related to EGFR-TKI resistance." (PMID 37388902, 2023). "The patient was considered as EGFR large fragment deletion positive if EGFR large fragment deletion was identified in the tumor tissue or plasma samples by targeted NGS." (PMID 36622089, 2023).